HMOX1 (heme oxygenase 1)
Diseases named in the same sentence as HMOX1 in open-access papers (continued):
Sharing a sentence is not in itself a finding about the gene and the disease.
Stroke (88 papers, 2010 to 2025). Sudden impairment of blood flow to a part of the brain due to occlusion or rupture of an artery to the brain. "Hmox1 encodes for the inducible Heme Oxygenase (HO1), which has been implicated in neuroprotection after stroke and is considered a possible therapeutic target." (PMID 35639208, 2022). "In addition, ADA-409-052 reduced the expression of stroke-induced Hmox1 that encodes heme oxygenase-1, an essential enzyme for iron-dependent LP during ferroptotic cell death." (PMID 33568697, 2021). "Specifically, PPARα KO led to increased expression levels of Gadd45b, Nppa, Hdc, Lcn2, Il6, Sox4, Marcksl1, Saa3, Ucn2, Met, Dusp10, Elovl7, Ngf, C3, Il11, Hmox1, Alox5, Tnfsf9, Angptl4, Plin2, H19, Csf2rb, Atf3, and Col7a1 following stroke." (PMID 40362325, 2025). "Studies from our group reported heme oxygenase‐1 (HO‐1) expression in astrocytes at 72 h post‐stroke in both the hippocampus and the cortex after transient MCAO in mice." (PMID 37715557, 2024). "In conclusion, HMOX1, TFR1 and SLC3A2 act as potential biomarkers of a stroke and play an important role in the underlying mechanism of stroke through the activation of ferroptosis." (PMID 37894877, 2023). "Three genes (orange), golgin subfamily B member 1 (GOLGB1), α-galactosidase A (GLA), and heme oxygenase-1 (HMOX1), are both SARS-CoV-2 host genes as well as stroke-associated genes." (PMID 33732102, 2021). "Meanwhile, SARS-CoV-2 host genes, such as ACTB, KPNA2, and JUN, interact with SAMHD1, VCAM1, and HMOX1, in the PPI network, indicating possible mechanisms of COVID-19 associated stroke." (PMID 33732102, 2021). "In consistency with other studies, our results revealed that several heat stroke proteins, including HMOX1, Hspa1a and Hp, were significantly up-regulated after heat exposure." (PMID 32436952, 2020). "NRF2 target genes include several antioxidant enzymes including PRDX1, thioredoxin 1 (TXN1), and heme oxygenase 1 (HMOX1) and its activation affords protection in animal models of stroke." (PMID 32733466, 2020). "In line with our results, many genes/proteins such as Hmox1, Gadd45, Ets-1, and Stat3 which are previously shown to be deregulated following stroke were also reported in our study." (PMID 29516010, 2018). "Our previous studies also demonstrated that Nrf2/heme oxygenase-1 (HO-1) pathway is a potential target for the neuroprotection against stroke." (PMID 29383171, 2017). "The nuclear factor erythroid-2-related factor 2 (Nrf2)/heme oxygenase-1 (HO-1) pathway has been considered a potential target for neuroprotection in stroke." (PMID 25384416, 2014). "Epicatechin has protected neurons against stroke and oxidative stress by upregulation of Nrf2 cascade and heme oxygenase-1 (HO1) enzyme." (PMID 23840922, 2013). "Another study revealed that CDDO derivatives could provide neuroprotection against ischemic injury by upregulating heme oxygenase-1 (HO-1), suggesting that enhancing HO-1 expression may be a legitimate strategy for the therapeutic intervention of stroke." (PMID 38785551, 2024). "Iristectorin B may act as a protective agent against stroke by regulating ferroptosis, and SLC3A2, TFR1 and HMOX1 may serve as potential diagnostic biomarkers for stroke, providing additional evidence to support the importance of ferroptosis in stroke." (PMID 37894877, 2023). "Clinically, a randomized controlled trial study on 30 chronic stroke patients suggested that serum HMOX1 levels could be used as a biomarker of stroke." (PMID 37533068, 2023). "In addition, glutathione (GSH), catalase and heme oxygenase-1 (HO-1) reduced levels in various stroke models." (PMID 36232980, 2022). "Likewise, A. borbonica polyphenols and caffeic acid were reported to improve other ROS-detoxifying enzymes including catalase, GPx and heme oxygenase-1 deregulated by hyperglycemic condition in a mouse model of stroke and cerebral endothelial cells." (PMID 35624723, 2022).
Stroke (continued). "Furthermore, the roles of other stroke-associated genes, such as SAMHD-1, DDAH-1, HMOX1, LTC4S, ACTB, KPNA2, and JUN, in mediating stroke secondary to SARS-CoV-2 infection are required to be further explored experimental using COVID-19 patient samples or SARS-CoV-2 animal models." (PMID 33732102, 2021). "Furthermore, A. camphorata’s compounds may also help mitigate the neurotoxic effects of heme accumulation in intracerebral hemorrhage, with inhibition of heme oxygenase-1 (HO-1), a key enzyme in heme degradation, offering potential protective effects against stroke in animal models." (PMID 40429941, 2025). "Meanwhile, edaravone treatment has been shown to activate Nrf2, heme oxygenase 1, and SIRT1 in experimental models of traumatic brain injury, amyotrophic lateral sclerosis, and stroke." (PMID 40260386, 2025). "Totarol, isolated from the sap of Podocarpus totara, up-regulates the protein levels Akt, Nrf2, and heme oxygenase-1 (HO-1), increases the activity of GSH and SOD, suppresses oxidative stress, and produces a neuroprotective effect on stroke." (PMID 37458258, 2023). "Among the proteins that differ significantly in terms of their regulation of stroke through ferroptosis are TFR1, HMOX1 and SLC3A2." (PMID 37894877, 2023). "Notably, the administration of dimethyl itaconate to compensate for the deficiency of immunoresponsive gene 1/itaconate axis led to enhanced microglial heme oxygenase-1 expression, alleviated ischaemic brain injury, improved motor function and decreased mortality in IRG1−/− stroke animals." (PMID 34557667, 2021). "Sulforaphane treatment did not result in a greater Hmox1 response than stroke alone." (PMID 22911746, 2012).
Insulin resistance (87 papers, 2010 to 2025). Increased resistance towards insulin, that is, diminished effectiveness of insulin in reducing blood glucose levels. "HMOX1 levels are negatively associated with TT, LH, insulin resistance, oxidative stress, and inflammation; furthermore, low serum HMOX1 is an independent risk factor for PCOS." (PMID 38251965, 2024). "Moreover, up-regulation of HMOX-1 expression is also associated with beneficial effects on insulin resistance of a GMP-derived peptide in HepG2 cells." (PMID 37048349, 2023). "The induction of HMOX1 expression has been considered a potential treatment for reversing insulin resistance." (PMID 39873298, 2025). "In particular, HMOX1 protein plays a role in the complex pathophysiological cascade involved in insulin resistance mechanisms, oxidative stress, metabolic syndrome and cardiovascular diseases." (PMID 38942607, 2024). "Conversely, genetic deletion of HMOX1 in macrophages or hepatocytes protected mice from development of insulin resistance and inflammation in a model of diet-induced obesity." (PMID 38585264, 2024). "HMOX1 expression negatively correlated with insulin resistance as assessed by the homeostasis model assessment of insulin resistance (HOMA-IR)." (PMID 36118901, 2022). "Hemo oxygenase-1 (Hmox1) plays a pro-inflammatory role in driving insulin resistance in the liver and visceral fat compartments." (PMID 26899878, 2016). "For instance, it has been shown that losing Hmox1 expression in mice increases insulin resistance." (PMID 39873298, 2025). "Increased HMOX1 mRNA levels correlate with a high BMI and insulin resistance, and may be a compensatory mechanism to reduce oxidative stress and inflammatory status in adipose tissue." (PMID 38251965, 2024). "In addition, Hmox1-/- mice spontaneously developed insulin resistance and had reduced physical activity." (PMID 32992485, 2020). "Visceral fat and insulin resistance are related to metabolic disease, as a result of a decrease of HO-1 show elevation of reactive oxygen species (ROS) and diminished levels of the antioxidant gene heme oxygenase-1 (HO-1)." (PMID 31906399, 2020). "Heme oxygenase-1 (HO-1) is a microsomal enzyme induced in response to oxidative stress and inflammatory stimuli, which plays an important role in suppressing inflammation and insulin resistance." (PMID 25477711, 2014). "Together, these data suggest that fasting muscle HMOX1 may be upregulated to protect against oxidative-stress-induced insulin resistance, a response that may be lost in type 2 diabetes." (PMID 22474579, 2012). "This single finding indicates that reducing HMOX1 levels may help reduce insulin resistance." (PMID 39873298, 2025). "The same study also showed that when they specifically knocked out HMOX1 in macrophages in mice, they were resistant to HFD-induced weight gain, glucose intolerance, insulin resistance, hepatic steatosis, and inflammation." (PMID 39873298, 2025). "The insulin resistance in HepG2 cells can be improved by elevating the expression levels of nuclear factor erythroid 2-related factor 2 (Nrf2), superoxide dismutase (SOD), NADPH quinone oxidoreductase (NQO1), heme oxygenase-1 (HO-1), and glutathione peroxidase (GSH-Px)." (PMID 38671903, 2024). "Importantly, this study also demonstrated that increased HMOX1 expression was predictive of insulin resistance in a cohort of obese patients, suggesting that the presence of HMOX1 expression is not necessarily indicative of a protective antioxidant state, and is context- and cell type-specific." (PMID 38585264, 2024).
Cognitive impairment (84 papers, 2015 to 2026). Abnormal cognition is characterized by deficits in thinking, reasoning, or remembering. "The protective effects of thymol on cognitive disorders are associated with the upregulation of the nuclear respiratory factor (Nrf2)/heme oxygenase-1(HO-1) pathway." (PMID 38665779, 2024). "The protective effects of thymol on cognitive deficits were associated with positive regulation of the nuclear respiratory factor (Nrf2)/heme oxygenase-1 (HO-1) pathway." (PMID 38029230, 2023). "In another study, Aβ-mediated hypomethylation of the heme oxygenase 1 (HMOX1) gene was noted to correlate with the development of cognitive impairment in AD." (PMID 35457077, 2022). "A recent study revealed that LPS induces cognitive deficits and iron accumulation in the hippocampi and cortices of aged mice by upregulating microglial heme oxygenase-1 (HO-1) expression." (PMID 34997032, 2022). "Researchers also indicated that the up-regulation of nuclear respiratory factor (Nrf2)/heme oxygenase-1(HO-1) pathway is entwined with the protective effects of thymol on cognitive impairments." (PMID 34298986, 2021). "Chronic HIV infection associates with reduced brain frontal cortex expression of the antioxidant/anti-inflammatory enzyme heme oxygenase-1 (HO-1) and increased neuroinflammation in individuals with cognitive impairment." (PMID 32669339, 2020). "Cognitive impairment in AD patients was strongly correlated with HMOX1 methylation status at this specific site." (PMID 27058954, 2016). "We evaluated DNA methylation status of HMOX1 at −374 promoter CpG site in blood samples from AD patients, patients with mild cognitive impairment (MCI), and control individuals using quantitative methylation-specific polymerase chain reaction." (PMID 27058954, 2016). "HMOX1 is highly expressed in hippocampal and cortical astrocytes and neurons in patients with AD or mild cognitive impairment (MCI), where it co-localizes with senile plaques, neurofibrillary tangles, corpora amylacea, and other factors." (PMID 27058954, 2016). "MSC-EVs alleviate cognitive impairment by suppressing hippocampal ferroptosis in dNCR-aged mice, mediated by stimulating heme oxygenase-1 (HO-1), silent information regulator 1 (SIRT1), and factor nuclear factor-erythroid 2-related factor 2 (Nrf2) signaling pathways." (PMID 38922501, 2024). "The scavenging of reactive oxygen species (O2− and H2O2) by the nuclear factor erythroid 2-related factor 2 and heme oxygenase-1 (NRF2/HO-1) signaling pathway was the primary method to achieve the goal of anti-oxidation, and a promising factor for improving the cognitive impairment seen in AD." (PMID 38068844, 2023). "Moreover, the exogenous addition of tCA has been shown to induce the expression of nuclear factor-E2-related factor 2 (Nrf2) and heme oxygenase-1 (HO-1), thereby increasing the effect of treadmill exercise on learning and memory in cognitive impaired mice." (PMID 34104079, 2021). "Our results indicate that the flavanol-regulated expression of HMOX1 in blood could be a mechanism that supports neuronal health, a finding that agrees with the assessment that a diet rich in flavonoids may confer therapeutic benefits to individuals suffering from cognitive deficits." (PMID 36771351, 2023). "It has been reported that Nrf2 increases the transcription of heme oxygenase-1 (HO-1) and NAD(P)H: quinone oxidoreductase 1 (NQO1) that mitigates the oxidative stress and inflammation of the brain and eventually improves the cognitive impairment in T2DM." (PMID 36247985, 2022). "In another study, where cognitive impairment and oxidative damage were induced in mouse models by aluminum chloride and D-galactose, kinetin had the ability to enhance the antioxidant system of the cell by increasing the activities of SOD, GSH-px, and heme oxygenase 1 (HO-1)." (PMID 35406107, 2022).
neuroblastoma (84 papers, 2013 to 2025). Neuroblastoma (NB) is the most common solid, extracranial childhood tumor. "Yet, NRF2 was also shown to be activated by withaferin A leading to induction of its bona-fide target gene heme oxygenase 1 (HMOX1) which causes an excess of cytosolic labile iron through catalysing its release from haeme promoting ferroptosis in neuroblastoma." (PMID 31936571, 2020). "In the present study we show that CBR-470-1 activates the Nrf2 cascade in SH-SY5Y neuroblastoma cells, causing disassociation of the Keap1-Nrf2 complex, cytosol Nrf2 protein stabilization and nuclear translocation, followed by increased expression of Nrf2 pathway genes (HMOX1, NQO1 and SOD1)." (PMID 32649311, 2020). "Activation of the nuclear transcription factor erythroid 2-related factor 2 (Nrf2)/heme oxygenase-1 (HO-1) pathway significantly attenuates oxygen-glucose deprivation (OGD)-induced damage in human neuroblastoma cells." (PMID 40949877, 2025). "For example, withaferin A induces ferroptosis in neuroblastoma cells via enhanced iron accumulation and ROS production mediated by HMOX1." (PMID 40137309, 2025). "Withaferin A, a natural ferroptotic agent, induced ferroptosis in neuroblastoma by promoting iron accumulation and ROS production through the upregulation of HMOX1." (PMID 38245706, 2024). "Chemical-induced ferroptotic cell death driven by increased HMOX1 expression was observed in HT-1080, neuroblastoma and glioblastoma cell lines." (PMID 38982523, 2024). "Chenet and coworkers (2019) demonstrated that a pretreatment of 4 h with carvacrol promotes mitochondrial protection in the human neuroblastoma cells SH-SY5Y exposed to hydrogen peroxide by a mechanism involving heme oxygenase-1." (PMID 37047044, 2023). "Specifically, roxadustat reversed MPTP-induced SH-SY5Y neuroblastoma cell apoptosis, upregulated mitochondrial respiration and counterbalanced oxidative stress by upregulating Nrf-2, heme oxygenase-1 (HO-1) and superoxide dismutase 2 (SOD2)." (PMID 35281917, 2022). "Kahweol has been shown to protect DNA from oxidative stress by inducing HMOX1 to control intracellular ROS levels in human neuroblastoma cells." (PMID 34500601, 2021). "The negative effects of curcumin treatment in the reduction of intracellular heme level have been reported in SH-SY5Y (human neuroblastoma) cells by upregulating heme oxygenase 1 (HO-1), a rate-limiting enzyme responsible for heme degradation." (PMID 35008835, 2021). "Furthermore, CBD regulates the expression of the induced antioxidant enzyme heme oxygenase-1 (HO-1) in keratinocytes, adipose tissue-derived mesenchymal stem cells, neuroblastoma cells and smooth muscle." (PMID 38111585, 2023). "Similarly, high NRF2 activity promoted high levels of heme oxygenase 1 (HMOX1), which acts detoxifying heme into biliverdin, releasing redox-active iron and, consequently, inducing lipid peroxidation in neuroblastoma and fibrosarcoma cells." (PMID 35803910, 2022). "Similarly, we observed HMOX1 upregulation, involved in increasing the labile iron pool, in cystine-deprived neuroblastoma cells before ferroptosis induction." (PMID 35484422, 2022). "To find out whether changes in the ganglioside pattern might be affected by an increased oxidative stress associated with Hmox1 knockout, we investigated the regulation of glycosphingolipid (GSL) synthesis using SH-SY5Y neuroblastoma cells rich in gangliosides." (PMID 30327713, 2018). "Furthermore, withaferin A promotes neuroblastoma (NB) cell death by increasing LIP levels through Hmox1, in addition to inactivating GPX4." (PMID 38267442, 2024). "4-F4t-NeuroP was injected into neuroblastoma cells (SH-SY5Y) and rodents, demonstrating a neuroprotective effect by regulating the transcriptional level of the antioxidant enzyme heme oxygenase-1." (PMID 36674450, 2023). "Research has shown that AST elevated the expression of heme oxygenase-1 (HO-1) and reduced oxidative stress in SH-SY5Y neuroblastoma cells." (PMID 32963732, 2020).
neuroblastoma (continued). "Another paper reported that Nrf2, heme oxygenase 1 (HO-1), and GSH are up-regulated in bortezomib-resistant neuroblastoma." (PMID 27655642, 2016). "An in vitro study with the human neuroblastoma SH-SY5Y cell line observed that TUDCA prevented oxidative stress through the highest expression of NRF2, DJ-1, and antioxidant enzymes heme oxygenase-1 (HO-1) and glutathione peroxidase (GPx), corroborating with our results." (PMID 37762363, 2023). "In respect to MYCN, a study showed that the aggressive neuroblastoma cell line HTLA-230 bearing MYCN amplification was slightly sensitive to bortezomib (BTZ), a selective inhibitor of the proteasome, due to NRF2 activation and subsequent upregulation of the antioxidant heme oxygenase-1 (HO-1)." (PMID 37835497, 2023). "Upregulated expression of antioxidant genes, viz., HMOX1, NFE2l2, SLC7A11, and NADPH oxidase, and downregulated expression of monooxygenase enzymes in our study could be a putative approach to deal with the oxidative stress in WS-treated human neuroblastoma SK-N-SH cells." (PMID 40636521, 2025).